TSPAN8 (tetraspanin 8)
Diseases named in the same sentence as TSPAN8 in open-access papers (continued):
Sharing a sentence is not in itself a finding about the gene and the disease.
tumor (continued). "A previous study using non‐neuronal tumor cells reported that exosome‐uptake requires internalization‐prone membrane domains and proposed that TEMs, containing tetraspanin 8 (Tspan8), contribute to target cell selection." (PMID 38938373, 2023). "For example, both CD9 and CD82 are tetraspanins that function to primarily suppress tumor growth, whereas Tspan8 and CD151 are primarily oncogenic." (PMID 35280793, 2022). "Using an xenogenic mouse model, it has been shown that specific antibodies to Tspan8 reduce cell motility and block tumor angiogenesis in vivo." (PMID 36613908, 2022). "In one study, tumor cells released exosomal tetraspanin (Tspan8), a key angiogenesis modulator, functioning via VEGF-independent pathways to stimulate endothelial cell proliferation and migration." (PMID 35664698, 2022). "The expression level of TSPAN8 in tumor tissues (TTs) and normal adjacent tissues (NATs) was determined by tissue microarray analysis, including 87 PDAC patients." (PMID 34163029, 2021). "The establishment of the critical role of the EGF-ERK-SOX9-TSPAN8 signaling cascade in promoting tumor metastasis makes TSPAN8 a novel therapeutic target for the treatment of PDAC." (PMID 34163029, 2021). "A study on a pancreatic cancer cell line showed that TSPAN8 expression leads to the development of disseminated intravascular coagulation and hemorrhage at the tumor site, as well as in metastatic tumors." (PMID 34830819, 2021). "In case of CD151, it is suggested to act in concert with TSPAN8 to drive exosome production in both tumor and endothelial cells, thereby facilitating tumor metastasis." (PMID 33919420, 2021). "An early study of tumor-EV content involved in angiogenesis demonstrated the abundant presence of cell membrane and EV-bound tetraspanin-8 (Tspan8), upregulated VEGFR and CD31 in endothelial cells (ECs), accelerating angiogenesis in a rat model of PDA." (PMID 34207163, 2021). "TSPAN8 expression in tumor cells is related to increased metastasis, proliferation, induction of angiogenesis and thrombosis." (PMID 34222025, 2021). "Many of the genes upregulated in these tumor initiating cells were expressed in our Cluster 1 cells including Tff3, Tspan8, Gpc3, Ly6d, Cldn2." (PMID 33173221, 2020). "Still, metastasis of PaCa cells transplanted into either TSPAN8−/− or TSPAN8−/−/CD151−/− mice is effectively inhibited, suggesting that host Tspan8 or CD151 can significantly affect tumor progression." (PMID 32878635, 2020). "TSPAN8 promotes the progression and metastasis of colorectal cancer by enhancing tumor cell movement and deregulating cell adhesions by altering the surface expression or activity of integrins and CD44." (PMID 32138170, 2020). "The expression level of TSPAN8 is elevated in malignant glioma tissues and is correlated with tumor grading." (PMID 32138170, 2020). "More importantly, we showed that Tspan8 function hinges on the dialog between tumor cells and neighboring keratinocytes." (PMID 32455575, 2020). "In contrast, tumor nodules remained close to DEJ with less dermal invasion when treated with Tspan8 mAb." (PMID 32455575, 2020). "TEX were derived from non-metastatic BSp73AS (AS) or metastatic BSp73ASML (ASML) rat tumor lines transfected with Tspan8 (AS-Tspan8) or Tspan8-shRNA (ASML-Tspan8kd)." (PMID 32013145, 2020). "In support of the in vitro data, the Siglec-4 spacer CAR displayed a similar anti-tumor efficacy in vivo as the cognate CD8α spacer CAR against TSPAN8 and both therapies were superior to the IgG4-based spacer CAR treatment." (PMID 32849600, 2020). "Tspan8, as a regulator of EVs content and function, can mediate EV amount increase in cell culture and in the circulation in tumor-bearing animals." (PMID 32443642, 2020). "Transmission electron microscopy revealed vesicles of approximately 100 nm diameter in the EV preparations from the blood of animals harbouring MTPa and MTPa‐Tspan8 tumours." (PMID 30982971, 2019).
tumor (continued). "Increasing evidence suggests that TSPAN8 promotes tumor cell migration, invasion, and metastasis in multiple types of human cancers, including ovarian and gastric colorectal cancers, hepatocarcinoma, pancreatic adenocarcinoma, and glioma." (PMID 31253779, 2019). "As a regulator of the content and function of extracellular vesicles (EVs), Tspan8 mediated a several‐fold increase in EV number in cell culture and the circulation of tumour‐bearing animals." (PMID 30982971, 2019). "It should be mentioned that to test for a link between TSPAN8 expression in primary tumours and the corresponding metastases, we were able to use 14 samples where both the primary tumour and the metastases originated from the same patient." (PMID 30982971, 2019). "In contrast, TSPAN8 overexpression-enhanced tumor growth, but this enhancement was inhibited by the expression of ATXN3 shRNA." (PMID 31253779, 2019). "With regard to the analysis of CD44v6 activities in tumor progression, the links between CD44v6 and Tspan8 can impede an unequivocal assignment." (PMID 31485223, 2019). "In this short review, we summarize the main functions of Tspan8/Co-029 and its role in the biology of tumor cells." (PMID 30769765, 2019). "Increased Tspan8 expression in tumor tissues (colorectal and ovarian cancer, melanoma, hepatocellular and pancreatic carcinoma) is generally related to worse prognosis." (PMID 30769765, 2019). "Weak and heterogeneous Tspan8 fluorescence was observed in the liver and spleen metastases of rats harbouring the MTPa‐Tspan8 tumours." (PMID 30982971, 2019). "The second aspect relates to the intensity ratio of Tspan8 in tumor compared to normal tissues, which is another crucial issue that needs to be addressed in order to avoid side effects." (PMID 30769765, 2019). "Of note, TSPAN8 depletion had limited effect on spheres forming ability of tumor cells treated with Hh inhibitors." (PMID 31253779, 2019). "Tspan8/Tspan8-TEX engage in crosstalk with the tumor stroma and premetastatic niche tissue and promote EC progenitor maturation and activation." (PMID 31921628, 2019). "For example, the tetraspanin CD82 is downregulated during metastases, while the tetraspanin CD151 and tetraspanin 8 are induced and able to support tumor progression." (PMID 31437164, 2019). "Coupled with exosomal expression of ectopic Tspan8, shown to enhance internalization by cancer cells, it was sufficient to inhibit tumor growth, motility, and invasion, especially by affecting stemness traits." (PMID 31737071, 2019). "Briefly, the starting material will be appropriate and sufficient for an in-depth elaboration of most aspects of CD44v6- and Tspan8-promoted tumor progression in cells and TEX, only some of which are hit by our analysis so far." (PMID 31485223, 2019). "We next used a genetic approach with a therapeutic potential to modulate TSPAN8 expression in tumor." (PMID 31253779, 2019). "IHC and immunoblotting analyses showed corresponding reduction of TSPAN8 in tumor tissues expressing TSPAN8-shRNA." (PMID 31253779, 2019). "Studies on human tumor cells reported associations between tetraspanin expression and tumor progression showing both reduced (CD82, CD9) and increased expression (CD151, Tspan8) in various cancer types." (PMID 29896201, 2018). "In the web of tetraspanins, CD151 and Tspan8 have high relevance for tumor progression and modulation of the tumor microenvironment." (PMID 28098821, 2017). "Tspan8 overexpression in human carcinomas has been suggested to play a role in tumor progression since forced Tspan8 expression in various cell lines facilitated metastasis in mice." (PMID 28188308, 2017). "Several studies reported the presence of TSPAN8 in the blood as a component of tumor-derived exosomes or as candidate mRNAs for detection of CRC." (PMID 28423546, 2017). "Here, we address the feasibility of RIT approach by targeting a novel tumor specific antigen: TSPAN8, using the monoclonal antibody Ts29.2." (PMID 28423546, 2017).
tumor (continued). "Exosomes derived from a pancreatic tumor cell line overexpressing tetraspanin 8 (Tspan8 or D6.1A) are able to promote tumor growth by their capacity to induce angiogenesis both in vitro and in vivo." (PMID 28257101, 2017). "Similar angiogenic effects were observed with exosomes derived from different tumor lines expressing Tspan8 and integrin α4." (PMID 28977990, 2017). "TSPAN8 was predominantly distributed on the cell membrane, and higher expression was observed in tumor compared to peri-tumor tissue." (PMID 27270327, 2016). "The data showed that high TSPAN8 expression was significantly correlated with tumor thrombus (P = 0.017), differentiation (P = 0.037), and TNM stage (P = 0.036)." (PMID 27270327, 2016). "We confirmed that over-expression of TSPAN8 resulted in an increase in tumor size and mesenteric lymph node metastasis in animal models of HCC." (PMID 27270327, 2016). "This is in contrast to the expectation that TSPAN8 would promote tumor growth, which was suggested by studies using nude mouse models of HCC." (PMID 27270327, 2016). "Except in rats receiving ASMLwt exosomes, tumor cells were hardly recovered particularly in lung and BM, indicating that both exosomal Tspan8 and CD151 contribute to niche preparation." (PMID 25544774, 2015). "Here, the effect of a Tspan8 antibody on colorectal cancer cells was investigated in tumor cell lines and in a xenogeneic mouse model." (PMID 26082723, 2015). "Based on this finding, the known contribution of exosomes to the metastatic process and the functional importance of exosomal tetraspanins, we controlled for the contribution of exosomal CD151 and Tspan8 in tumor progression." (PMID 25544774, 2015). "Tspan8 over-expression has been documented in different carcinomas which relates to an increased metastatic capacity of tumor cells and poor prognosis." (PMID 26082723, 2015). "We also find two cases of inversions involving exonic material in NKAIN3 and TSPAN8, a cell surface antigen, which were found to be overexpressed in some human tumor cell lines." (PMID 23171647, 2012). "CD151 and tetraspanin 8 support tumour progression; increased CD151 is an indicator of poor prognosis." (PMID 21339979, 2010). "Tetraspanins are small transmembrane proteins, such as CD9, CD37, CD53, CD63, CD81, CD82, CD151 and tetraspanin 8, that are involved in a multitude of biological processes, including cell-cell adhesion, metastasis suppression and tumour progression." (PMID 21339979, 2010). "TSPAN8, a tetraspanin family member, augments cellular basement membrane adhesion through integrin α6β4 localization regulation, providing anchorage sites for tumor cell vascular invasion." (PMID 41450464, 2025). "CLA, CD66c, CD318 and TSPAN8 were identified as putative target candidates from 371 tumor antigens." (PMID 38275818, 2024). "The diverse functions of TSPAN8 may contribute to its critical oncogenic roles in multiple stages of tumor development." (PMID 38275818, 2024). "In addition, fetal-I tumor organoids (hepatic-intermediate) expressed markers related to tumor progression and invasion, including TSPAN8, CKB, UCA1, and FXYD3." (PMID 39567475, 2024). "Moreover, TSPAN8-expressing exosomes are actively involved in tumor initiation, progression, and metastasis." (PMID 38275818, 2024). "Besides, a mAb targeting the LEL of Tspan8 inhibited the incidence of ovarian metastases in vivo and diminished tumor invasion in vitro." (PMID 38389703, 2024). "Importantly, the oncogenic roles of TSPAN8 in tumor development and cancer metastasis have gained prominence in recent decades." (PMID 38275818, 2024). "Since most of these studies are based on in vitro culture systems, further in vivo studies are needed to address how TSPAN8 transcription is switched on and its effects and significance in promoting tumor initiation, progression, and metastasis in different epithelial cancers." (PMID 38275818, 2024).
tumor (continued). "Interestingly, the expressions of α6β4 and TSPAN8 were primarily restricted to tumor cells, while other integrins and tetraspanins were present in the surrounding stromal cells." (PMID 38275818, 2024). "Injection of antibodies directed against tetraspanin 8 resulted in tumor reduction." (PMID 39031113, 2024). "Therefore, exosomal tetraspanin 8 is thought to promote tumor invasion and stimulate angiogenesis in all cancers." (PMID 39031113, 2024). "Tumor exosomes display Tspan8 and CD151 that stimulate angiogenesis and tumor progression." (PMID 37108809, 2023). "Since both the endothelin system and Tspan8 may favor tumor growth, this work opens the way for further investigation of potential targets for interfering with a synergistic effect that may be deleterious in the development of cancer." (PMID 37835445, 2023). "Convergence of Tspan8 and endothelin axis in tumor biology offers a new area of research." (PMID 37835445, 2023). "Recent evidence suggests that TSPAN8 has an important role in tumor invasion and metastasis in multiple types of tumors, including PDAC, ovarian carcinoma, gastric adenocarcinoma, colon adenocarcinoma, liver hepatocellular carcinoma, esophageal carcinoma, melanoma and glioma." (PMID 34163029, 2021). "Despite its well-established importance in tumor progression, metastasis and drug resistance, most previous studies have focused on how TSPAN8 interacts with other molecules and organizes membrane networks as a ‘molecular facilitator' to achieve its biological functions." (PMID 34163029, 2021). "Tspan8/CD151 exosomes contribute to tumour progression by stimulating angiogenesis in vivo." (PMID 34671031, 2021). "CAR T cells specific for CD66c, CD318 and TSPAN8 demonstrate efficacies ranging from stabilized disease to complete tumor eradication with CD318 followed by TSPAN8 being the most promising candidates for clinical translation based on functionality and predicted safety profiles." (PMID 33674603, 2021). "TSPAN8 mRNA expression is regulated by upstream promoters and TFs during tumor progression." (PMID 34163029, 2021). "Meanwhile, according to the relatively specific distribution of TSPAN8, a radiolabeled anti-TSPAN8 antibody was developed, which could inhibit tumor growth significantly in nude mice carrying HT29 tumors." (PMID 34540692, 2021). "Emerging evidence supports that TSPAN8 has an important role in tumor progression and metastasis." (PMID 34163029, 2021). "Interestingly, CD44v6 expression is correlated to Tetraspanin 8 (Tspan8) expression in PDA tumor cells derived-EVs, described in the context of ECM activation and angiogenesis, and is required for EV uptake in non-CIC cells." (PMID 34207163, 2021). "Notably, Tspan8-enriched exosomes produced by PaCa cells can induce VEGF-independent angiogenesis around tumor tissues." (PMID 32878635, 2020). "Moreover, tumor cells from this stage IV sample show upregulation of genes related to EMT, angiogenesis, and metabolic pathways, including those that have been previously associated with tumor progression such as MMP1, S100A2, TSPAN8, and IGFBP2." (PMID 33170151, 2020). "Finally, we investigated the functionality of the three TSPAN8 specific CAR constructs in vivo in a pre-clinical PDAC tumor model." (PMID 32849600, 2020). "In conclusion, currently available and accumulating evidence has led us to speculate that antibody-based targeting of TSPAN8 may be an effective strategy to suppress tumor progression and metastasis." (PMID 32138170, 2020). "Some tetraspanins such as CD9, CD82, and CD151 are present in almost every EV subtype, while other tetraspanin members are only expressed in particular cell lines and tissues, such as Tssc6 in hematopoietic cells, CD37 and CD53 in immune cells, and Tetraspanin-8 (Tspan8) in tumor cells." (PMID 33003285, 2020). "In brief, Tspan8 contributes to tumor progression at different levels of the metastatic cascade." (PMID 31921628, 2019).
tumor (continued). "An even‐stronger effect of Tspan8 was observed after intraperitoneal injection of tumour cells." (PMID 30982971, 2019). "Consequently, the TSPAN8 expression promoted cancer cell stemness, resistance of CSCs to chemotherapeutic agents, and tumor formation in mice." (PMID 31253779, 2019). "Our quantitative results showed that TSPAN8 depletion reduced tumor growth." (PMID 31253779, 2019). "We observed that the expression levels of TSPAN8 in primary tumours and in the corresponding metastases differed from each other, indicating that expression thereof may change during tumour progression." (PMID 30982971, 2019). "It is likely that Tspan8 interacts with different proteins in different tumour types." (PMID 30982971, 2019). "Since CD44v6 has been shown to affect Tspan8 expression, this would functionally link two PaCIC markers in a platform that could contribute to tumor progression via TEX." (PMID 31485223, 2019). "TSPAN8 overexpression markedly enhanced the tumor-forming ability and stem cell frequency and shortened mouse survival time, whereas TSPAN8 depletion reduced the tumor-forming ability, stem cell frequency and prolonged mouse survival time compared with control group." (PMID 31253779, 2019). "Cross talk between tumor-derived EVs and the matrix is strongly influenced by EV tetraspanins (CD151 and Tspan8), mainly due to their associations with integrins (ITGA3, ITGB4, and ITGAM) and proteases (MMP2, MMP9, MMP14, and CD13), which facilitate binding, motility, and matrix degradation." (PMID 29760691, 2018). "Moreover, a mAb reacting with the LEL of Tspan8 inhibited tumor invasion in vitro and diminished incidence of ovarian metastases in vivo." (PMID 29946318, 2018). "Also another tetraspanin, Tspan8, in complex with integrin subunit CD49d (α4), has been shown to mediate the selective binding and uptake of tumor EXOs by endothelial cells, leading to their activation and proliferation." (PMID 29760691, 2018). "Furthermore,TSPAN8-specific antibodies reduce cell motility, angiogenesis, xenografted-tumor growth in nude mice and metastasis incidence." (PMID 28423546, 2017). "Notably, flow cytometry of the gated tumor cell population and immunohistochemistry of the matrigel plug showed partial regain of CD44v6 expression and upregulated Tspan8, α6β4 and CXR4 expression in A818.4-CD44v6kd cells of holoclone TEX-treated mice." (PMID 27419629, 2016). "Recent evidence indicates that tetraspanin-8 (TSPAN8) promotes tumor progression and metastasis." (PMID 27270327, 2016). "Thus, CD151- and Tspan8-competent tumor exosomes support matrix degradation, reprogram stroma and hematopoietic cells and drive non-metastatic ASML-CD151/Tspan8kd cells towards a motile phenotype." (PMID 25544774, 2015). "Binding of the Tspan8 antibody to the tumor cells may modify their response to the tumor microenvironment possibly by disrupting the assembly of tetraspanin microdomains containing integrins, growth factor receptors, and/or signaling molecules." (PMID 26082723, 2015). "This suggests that the expression of TSPAN8 occurs very early during tumour development." (PMID 21081927, 2011). "Although further studies on larger series of melanocytic lesions will be necessary to confirm these findings, the idea of early spread led us to speculate that TSPAN8 might identify metastatic cells arising from early primary tumours." (PMID 21081927, 2011). "CD151 and TSPAN8 could also be identified as biomarkers for tumor cells in the primary tumor." (PMID 38255741, 2024). "Similarly, angiogenesis induced by TSPAN8 in rat tumor models could be effectively inhibited by the anti-rat TSPAN8 specific antibody D61.A." (PMID 38275818, 2024). "TSPAN8—chosen for its highest expression among differentially expressed genes in the tumor compartment of stage 4 primary CC tissues—exhibited significant overexpression in the tumor compartment in comparison to the stroma region, including immune and fibroblast compartments." (PMID 38255741, 2024).